AQP11 (aquaporin 11)
Diseases named in the same sentence as AQP11 in open-access papers (continued):
Sharing a sentence is not in itself a finding about the gene and the disease.
Alzheimer disease (1 paper, 2024). A progressive, neurodegenerative disease characterized by loss of function and death of nerve cells in several areas of the brain leading to loss of cognitive function such as memory and language. "The themes of up-regulating AQP0 and AQP11 in response to cellular stress were consistent with proposed compensatory or protective roles for these channels, potentially relevant in conditions such as Alzheimer’s disease, where oxidative stress is prominent." (PMID 38451099, 2024). "In conclusion, work here proposes that up-regulation of AQP0 and AQP11 expression could be an adaptive mechanism to reduce the toxic effects H2O2 accumulation, alleviating damage associated with neurodegenerative diseases such as Alzheimer’s disease, in which oxidative stress is prominent." (PMID 38451099, 2024).
autism (1 paper, 2009). Persistent deficits in social interaction and communication and interaction as well as a markedly restricted repertoire of activity and interest as well as repetitive patterns of behavior. "AQP11 is expressed in the Purkinje cells of the brain cerebellar, a site that have been implicated in the pathophysiology of autism." (PMID 19607658, 2009).
autoimmune disease (1 paper, 2016). A disorder resulting from loss of function or tissue destruction of an organ or multiple organs, arising from humoral or cellular immune responses of the individual to their own tissue constituents. "Since AQP11 is a protein which function is still discussed and this was the first association of this protein with an autoimmune disease, we were interested to further characterize the meaning of AQP11 downregulation for ERU pathogenesis." (PMID 27107718, 2016).
brain injuries (1 paper, 2025). "In this review, we present and discuss the findings from clinical and experimental studies on AQP4, AQP2, AQP9, and AQP11 in acute brain injuries." (PMID 40564125, 2025). "Among them, AQP2, AQP4, AQP9, and AQP11 have been implicated in traumatic and non-traumatic brain injuries." (PMID 40564125, 2025). "Hence, targeting AQP11 in the cerebral endothelium may offer a new strategy to preserve BBB integrity in acute brain injuries." (PMID 40564125, 2025).
chromophobe renal cell carcinoma (1 paper, 2022). Chromophobe renal cell carcinoma is a rare subtype of renal cell carcinoma, originating from the intercalating cells of the collecting ducts and macroscopically manifesting as a well-circumscribed, highly lobulated, solid tumor that is usually diagnosed at an early stage. "AQP11 was expressed at lower levels in clear cell renal cell carcinoma (fold change = −1.944) and chromophobe renal cell carcinoma (fold change = −4.694) samples than in corresponding normal samples." (PMID 36254092, 2022).
cystic liver disease (1 paper, 2016). Cystic disease of the liver is rare and can take several forms. "Using Aqp11 gene knockout mice, Ishibashi and coworkers suggested a role for hepatocyte AQP11 in cystic liver disease." (PMID 27409609, 2016).
enteritis (1 paper, 2016). Inflammation of the small intestine. "On the other hand, the downregulated expression of several AQPs (AQP1, AQP3, AQP4, AQP7, AQP8, AQP10 and AQP11) in the small and large intestines has been observed in the process of either enteritis or diarrhea." (PMID 27589719, 2016).
Insulin resistance (1 paper, 2020). Increased resistance towards insulin, that is, diminished effectiveness of insulin in reducing blood glucose levels. "Accordingly, adipose tissue fraction analysis also revealed an increase (p <0.05) in AQP11 mRNA levels in adipocytes in comparison to SVFC, independently of the insulin resistance degree." (PMID 32512939, 2020).
kidney cancer (1 paper, 2022). Primary or metastatic malignant neoplasm involving the kidney. "However, research on the potential relationship between AQP11 and kidney cancer is insufficient." (PMID 35245343, 2022).
morbid obesity (1 paper, 2020). An excess of body weight, normally defined as an individual with a body mass index greater than 35 or a body weight greater than one hundred percent of ideal body weight. "AQP11 expression was assessed in 67 paired visceral and subcutaneous adipose tissue samples obtained from patients with morbid obesity and normal-weight individuals." (PMID 32512939, 2020).
Obesity (1 paper, 2020). Accumulation of substantial excess body fat. "However, obesity and obesity-associated T2D were associated with increased (p < 0.05) AQP11 mRNA and protein levels in omental adipose tissue, without changes in subcutaneous fat." (PMID 32512939, 2020). "To gain further insight into the role of AQP11 in the onset of obesity, we evaluated the expression and subcellular location of this superaquaporin during adipocyte differentiation and lipolysis." (PMID 32512939, 2020). "Together, it seems plausible that, in obesity, the overexpression of AQP11 also alleviates inflammation-induced ER stress in visceral adipocytes due to its peroxiporin activity." (PMID 32512939, 2020). "Targeting AQP11 to reduce ER stress might constitute a potential therapeutic target for the treatment of obesity." (PMID 32512939, 2020). "Owing to its “peroxiporin” properties, AQP11 overexpression in visceral fat might constitute a compensatory mechanism to alleviate ER stress in obesity." (PMID 32512939, 2020). "Thus, it seems plausible that the herein observed upregulation of AQP11 mRNA and protein levels in visceral fat might constitute a compensatory mechanism to protect adipocytes against ER stress induced by lipotoxicity in obesity." (PMID 32512939, 2020). "Since AQP11 is an endoplasmic reticulum (ER)-resident protein that transports water, glycerol, and hydrogen peroxide (H2O2), we hypothesized that this superaquaporin is involved in ER stress induced by lipotoxicity and inflammation in human obesity." (PMID 32512939, 2020).
Seizure (1 paper, 2022). A seizure is an intermittent abnormality of nervous system physiology characterized by a transient occurrence of signs and/or symptoms due to abnormal excessive or synchronous neuronal activity in the brain. "Altogether, these results indicate that DPA suppresses the ferroptosis process via activation of Aqp11 in KA-induced seizure model." (PMID 36009321, 2022).
cancer (6 papers, 2018 to 2023). A tumor composed of atypical neoplastic, often pleomorphic cells that invade other tissues. "In colorectal cancer, downregulation of AQP11 is associated with cancer progression acting through an axis along with miR-152-3p." (PMID 38136293, 2023). "Cell line experiment suggested that, among eleven cancer cell lines with AQP11 expression, there was a significant association of AQP11 expression with cisplatin resistance." (PMID 35847914, 2022). "There are only a few studies that indicate a possible role of AQP11 in cancer." (PMID 38136293, 2023). "Surprisingly, the most pronounced difference was observed for AQP11, an intracellular membrane protein, which was present in cancer cell lines, but was absent in nontumorigenic cell line." (PMID 37175840, 2023). "Different from other AQPs, there was no previous study about the role of AQP10 and AQP11 in human malignant tumors." (PMID 29472315, 2018).
tumor (5 papers, 2021 to 2025). "AQP11 AQP11 encodes a water-channel membrane protein that is downregulated in CRC and facilitates tumor cell proliferation, migration, invasion, and adhesion." (PMID 41583431, 2025). "Analysis of the GSE39582 dataset revealed notably elevated expression of CCDC34, FBL, and RAB15 in tumor tissues, whereas AQP11 and HADH were notably downregulated." (PMID 41583431, 2025). "By integrating these data, the expression of AQP11 was found to be significantly lower in tumor tissues but inapparent to clinical stage and pathological grade." (PMID 36254092, 2022). "Furthermore, high AQP11 level seems to play a role as one of the pro-survival factors, protecting tumor cells from cisplatin-induced stress." (PMID 35847914, 2022). "Furthermore, patients with high tumor AQP11 mRNA expression (10.3%) had significantly worse overall survival compared with patients with low AQP11 expression." (PMID 35847914, 2022). "According to the GEPIA database, AQP1, AQP3, AQP4, and AQP9 were significantly expressed in LUAD tissues compared to normal lung tissues (p < 0.05), but some genes including AQP0, AQP5, AQP6, AQP7, AQP8, AQP10, and AQP11 were not differentially expressed between tumor and normal tissues." (PMID 34708074, 2021).
infection (3 papers, 2012 to 2024). The state of being infected such as from the introduction of a foreign agent such as serum, vaccine, antigenic substance or organism. "In response to infection, aquaporin (AQP11) expression was reduced, whereas ATPase transporters (ATP2A2, ATP7A) expression were significantly elevated." (PMID 39703373, 2024). "The HCV genome levels in AQP11-knocked down cells were about 3.2-fold lower than those in control siRNA-transfected cells 6 days after infection." (PMID 31046802, 2019). "Next, in order to examine whether HCV infection led to a reduction in AQP11 expression, we determined AQP11 expression levels in Huh7.5.1 cells following infection with HCVcc." (PMID 31046802, 2019). "AQP11 expression levels were significantly reduced by infection with HCVcc in Huh7.5.1 cells." (PMID 31046802, 2019). "In addition, several transporters are affected during infection, which might provide insight into a perturbed homeostasis during NCC because of ependymal cell activation, for example, a reduced expression of the aquaporin family member AQP11." (PMID 22731103, 2012).
kidney disease (3 papers, 2019 to 2025). "Some of the chosen genes were also linked to specific kidney disease phenotypes (Aqp11, Mpp5, Prcp)." (PMID 30625149, 2019). "However, other AQPs warrant investigation, such as aquaporin 11, a member of the superaquaporin subfamily, which has been genetically linked to renal diseases in both human studies and mouse models." (PMID 40072108, 2025).
AQP11 also shares sentences with these, for which no sentence is quoted: atrophic gastritis (1 paper); autosomal dominant polycystic kidney disease (1); clear cell renal cell carcinoma (1); colorectal cancer (1); diabetic macular edema (1); diabetic nephropathy (1); endometrial cancer (1); endometrioid ovarian cancer (1); glioblastoma (1); glioma (1); ischemic stroke (1); Kidney Cyst (1); kidney damage (1); neurodegenerative disease (1); retinal diseases (1); retinal edema (1); Sepsis (1); serous ovarian cancer (1); uveitis (1).